LINC00964 (long independently transcribed non-coding RNA 964)
Gene: Long non-coding RNA gene on chromosome 8 (124,823,702 to 124,962,531, forward strand). Ensembl gene ENSG00000249816.
Diseases named in the same sentence as LINC00964 in open-access papers:
LINC00964 is named in the same sentence as 5 diseases in open-access papers, as found by Europe PMC text mining. Sharing a sentence is not in itself a finding about the gene and the disease. The quoted sentences say what the papers report.
esophageal cancer (1 paper, 2018). A primary or metastatic malignant neoplasm involving the esophagus. "The results revealed that many lncRNAs dysregulation are accompanied with CNV, such as PVT1, LINC00887 and LINC00964 with frequency gain, LINC01415 and WEE2‐AS1 with frequency loss in esophageal cancer." (PMID 29926523, 2018). "Further somatic copy number variation analyses revealed that lncRNAs genome loci copy number amplifications or deletions are involved in part of lncRNAs dysregulation in esophageal cancer tissues, such as PVT1, LINC00887, LINC00964, LINC01415, and WEE2‐AS1." (PMID 29926523, 2018).
LINC00964 also shares sentences with these, for which no sentence is quoted: asthma (1 paper); atrial fibrillation (1); coronary artery disease (1); hepatocellular carcinoma (1).